HSPA12B (heat shock protein family A (Hsp70) member 12B)
Diseases named in the same sentence as HSPA12B in open-access papers (continued):
Sharing a sentence is not in itself a finding about the gene and the disease.
Anxiety (1 paper, 2018). Intense feelings of nervousness, tension, or panic often arise in response to interpersonal stresses. "Notably, HSPA12B Tg mice demonstrated more entries (97.1%) into open arms than WT mice did, suggesting a decreased anxiety in HSPA12B Tg mice post‐stroke." (PMID 29411514, 2018). "Moreover, overexpression of HSPA12B decreased stroke‐induced anxiety." (PMID 29411514, 2018).
Cerebral ischemia (1 paper, 2022). Restriction of arterial blood supply to the brain associated with insufficient oxygenation to support the metabolic requirements of the tissue. "In the rat model, SchB might alleviate the damage of inflammatory response to nerve cells during cerebral ischemia-reperfusion via regulating the HSPA12B/PI3K/Akt signaling pathway, indicating that SchB could inhibit the secondary inflammatory response after cerebral ischemia-reperfusion." (PMID 36313287, 2022).
COVID-19 (1 paper, 2025). A disease caused by infection with severe acute respiratory syndrome coronavirus 2. "Specifically, the SNP rs910652 HSPA12B has been associated with a decreased risk of severe COVID-19 in the entire group, females and patients with normal physical activity levels." (PMID 41009536, 2025). "According to the Lung Disease Knowledge Portal, rs910652 HSPA12B is linked to a reduced risk of very severe respiratory confirmed COVID-19 compared with the general population." (PMID 41009536, 2025). "SNP rs910652 HSPA12B (EA C) decreased the risk of severe COVID-19 in the entire group (p = 0.01), females (p = 0.04), and patients with normal physical activity levels (p = 0.01)." (PMID 41009536, 2025). "Conversely, in females, rs910652 HSPA12B (protective allele C, OR = 0.68, 95% CI 0.47–0.98, p = 0.04, pperm = 0.04) was associated with a decreased risk of severe COVID-19." (PMID 41009536, 2025). "Specifically, SNP rs7189628 DNAJA2 (risk allele T, OR = 2.02, 95% CI 1.26–3.24, p = 0.003, pperm = 0.002) was found to increase the risk of severe COVID-19, whereas SNP rs910652 HSPA12B (protective allele C, OR = 0.70, 95% CI 0.53–0.92, p = 0.01, pperm = 0.01) was associated with a reduced risk." (PMID 41009536, 2025). "According to the Lung Disease Knowledge Portal bioinformatic resource, first, rs910652 HSPA12B was linked to a lower risk of very severe respiratory confirmed COVID-19 cases, whereas rs6457452 HSPA1B was associated with an increase in hospitalization due to COVID-19." (PMID 41009536, 2025). "Moreover, the risk allele T rs910652 HSPA12B, through TF binding, may exacerbate COVID-19 outcomes by participating in the cellular response to prostaglandin E stimulus, promoting severe COVID-19 by impairing the immune response." (PMID 41009536, 2025). "Specifically, the polymorphic variants rs1136141 and rs1461496 HSPA8, rs1042665 HSPA9, rs7189628 DNAJA2, rs910652 HSPA12B, rs6457452 HSPA1B and rs1043618 HSPA1A are associated with alerted risk of severe COVID-19." (PMID 41009536, 2025). "Notably, for rs910652 HSPA12B was observed protective effects against severe COVID-19 in patients with normal physical activity levels: (protective allele C, OR = 0.58, 95% CI 0.39–0.88, p = 0.009, pperm = 0.007, (pbonf = 0.01))." (PMID 41009536, 2025). "Notably, two SNPs rs1136141 HSPA8 and rs7189628 DNAJA2 are associated with severe COVID-19 in patients under 68 years of age, whereas in older patients, SNPs rs1461496 HSPA8, rs910652 HSPA12B, rs1043618 HSPA1A and rs6457452 HSPA1B are significantly associated with severe disease." (PMID 41009536, 2025).
diabetes (1 paper, 2025). "Univariate Logistic regression analyses showed that a range of variables such as BMI, diabetes mellitus, fasting blood glucose, TG, and serum HSPA12B levels may be associated with the risk of sarcopenia." (PMID 39983811, 2025). "Moreover, our stratified analyses revealed low levels of HSPA12B were also associated with increased risk both in individuals with diabetes and without diabetes." (PMID 39983811, 2025).
diabetic nephropathy (1 paper, 2023). "The genes that contributed to the biological relevance of diabetic nephropathy, include gene TTN (rs72646845), PI16 (rs113848006), DPY6 (rs36027551), CROCC (rs41272737), PPP1R3A (rs1799999), ZNF136 (rs140861589), HSPA12B (rs6076550), and FRMD4A (rs1541010)." (PMID 37033211, 2023).
endothelial dysfunction (1 paper, 2015). In vascular diseases, endothelial dysfunction is a systemic pathological state of the endothelium (the inner lining of blood vessels) and can be broadly defined as an imbalance between vasodilating and vasoconstricting substances produced by (or acting on) the endothelium. "In this study, we observed that overexpression of HSPA12B attenuated LPS-induced inflammatory response in HUVECs, indicating that HSPA12B could improve endothelial dysfunction in inflammatory diseases." (PMID 25545050, 2015). "Our results suggest that HSPA12B may have a therapeutic potential against endothelial dysfunction." (PMID 25545050, 2015).
infarction (1 paper, 2015). A localised pathological necrosis of tissue resulting from obstruction of the blood supply usually by a thrombus, an embolus, or vascular torsion. "In supporting this observation, previous studies by ours and others have demonstrated that HSPA12B increased tube formation in endothelial cells and angiogenesis in myocardium post-infarction." (PMID 25909170, 2015).
ischemia (1 paper, 2016). A hypoperfusion of the BLOOD through an organ or tissue caused by a PATHOLOGIC CONSTRICTION or obstruction of its BLOOD VESSELS, or an absence of BLOOD CIRCULATION. "In this study we examined the effect of HSPA12B on acute myocardial ischemia/reperfusion injury, because I/R possesses unique pathological process compared with permanent ischemia without reperfusion." (PMID 27644317, 2016). "We have reported previously that HSPA12B attenuated cardiac remodeling at the chronic phase of permanent ischemia without reperfusion via an eNOS-mediated angiogenesis mechanism." (PMID 27644317, 2016). "Additionally, the HSPA12B Tg hearts exhibited a prominent improvement of no-reflow during reperfusion after ischemia." (PMID 27644317, 2016).
non-small cell lung carcinoma (1 paper, 2019). A group of at least three distinct histological types of lung cancer, including non-small cell squamous cell carcinoma, adenocarcinoma, and large cell carcinoma. "A similar mechanism has been found in non-small-cell lung cancer involving the negative regulation of Heat shock protein family A member 12B (HSPA12B) mRNA by uc.454 through direct interaction at the 3′UTR of HSPA12B mRNA." (PMID 31167408, 2019).
sarcopenia (1 paper, 2025). Progressive decline in muscle mass due to aging which results in decreased functional capacity of muscles. "Multivariate logistic regression analysis showed that decreased serum HSPA12B levels (<185.50 ng/mL) were a risk factor for increased risk of sarcopenia (adjusted odds ratio = 4.335, 95% CI = 3.136–5.993, P < 0.001)." (PMID 39983811, 2025). "Although we found for the first time that low serum HSPA12B levels are associated with an increased risk of sarcopenia in the elderly, our current study should be interpreted in the context of certain limitations." (PMID 39983811, 2025). "In conclusion, our findings suggest that lower serum HSPA12B levels are relevant to the risk of sarcopenia in older adults." (PMID 39983811, 2025). "Low serum HSPA12B level (<185.50 ng/mL) was associated with an increased risk of sarcopenia in older adults." (PMID 39983811, 2025). "To analyze the association between HSPA12B and the risk of sarcopenia, we first inspected the correlation between HSPA12B and clinical variables." (PMID 39983811, 2025). "Our present study showed for the first time that serum HSPA12B, a protein with protective effects on angiogenesis and endothelial function, was associated with sarcopenia in older adults." (PMID 39983811, 2025). "Our stratified analyses showed that the correlation between low HSPA12B levels and the risk of sarcopenia was prominent among participants over and under 80 years old." (PMID 39983811, 2025). "However, the exact correlation between HSPA12B levels and the risk of sarcopenia in older adults with different states still needs to be further demonstrated." (PMID 39983811, 2025). "However, more prospective studies with larger sample sizes from different regions are required to confirm the predictive role of circulating HSPA12B levels on the risk of sarcopenia." (PMID 39983811, 2025). "However, it remains unclear whether serum HSPA12B levels are associated with the risk of sarcopenia." (PMID 39983811, 2025). "However, the association of HSPA12B levels with sarcopenia remains unclear." (PMID 39983811, 2025). "Significantly, serum HSPA12B levels were lower in patients with sarcopenia (median [interquartile range] = 182.15 [137.58–225.86] ng/mL) than those without sarcopenia (228.96 [193.03–292.93] ng/mL) (P < 0.001)." (PMID 39983811, 2025). "In summary, our results indicate that low serum HSPA12B level is associated with an increased risk of sarcopenia in the elderly, suggesting a potential role of HSPA12B in the development of sarcopenia." (PMID 39983811, 2025). "Among 936 community-dwelling older adults, serum HSPA12B level was positively correlated with the components of sarcopenia, including skeletal muscle mass, grip strength, and gait speed." (PMID 39983811, 2025). "Third, although our results showed that serum HSPA12B was positively correlated with the components of sarcopenia; however, the correlation coefficients were relatively weak." (PMID 39983811, 2025). "Receiver operating characteristic curve analysis indicated that the optimal cut-off value of serum HSPA12B level for predicting sarcopenia was 185.50 ng/mL, with a sensitivity of 52.6% and a specificity of 80.8% (area under curve = 0.742, 95% confidence interval [CI] = 0.711–0.772, P < 0.001)." (PMID 39983811, 2025). "Therefore, we conducted a case-control study investigating the relationship between serum HSPA12B and sarcopenia in Chinese community-dwelling older adults." (PMID 39983811, 2025). "Therefore, our findings indicate that HSPA12B may prevent the process of skeletal sarcopenia by promoting neovascularization." (PMID 39983811, 2025). "We found that serum HSPA12B levels in patients with sarcopenia (median [interquartile range] = 182.15 [137.58–225.86] ng/mL) were lower than those in elderly people without sarcopenia (228.96 [193.03–292.93] ng/mL, P < 0.001)." (PMID 39983811, 2025).
sarcopenia (continued). "However, we showed here that serum HSPA12B levels were lower in patients with sarcopenia than nonsarcopenic subjects." (PMID 39983811, 2025).
Stroke (1 paper, 2018). Sudden impairment of blood flow to a part of the brain due to occlusion or rupture of an artery to the brain. "HSPA12B Tg mice demonstrated a significant higher survival rate than WT mice within 28 days post‐stroke." (PMID 29411514, 2018). "Immunoblotting analysis revealed that p‐eNOS/eNOS ratios were increased significantly in ischaemic hemispheres of WT and HSPA12B Tg mice at day 7 post‐stroke, respectively, compared with their sham controls (P < 0.01 or 0.05)." (PMID 29411514, 2018). "Stroke‐induced hippocampal degeneration was attenuated in HSPA12B Tg mice examined at day 28 post‐stroke." (PMID 29411514, 2018). "Neurological function was also evaluated in HSPA12B Tg mice post‐stroke following L‐NAME administration." (PMID 29411514, 2018). "As expected, HSPA12B Tg mice demonstrated a significant higher survival rate than WT mice did within 28 days post‐stroke (P < 0.05)." (PMID 29411514, 2018). "To clarify the roles of eNOS activation in HSPA12B‐induced neuronal protection at chronic phase of stroke, we treated mice with L‐NAME, a widely used eNOS inhibitor in HSPA12B Tg mice." (PMID 29411514, 2018). "In line with the effect of L‐NAME on neurological recovery in HSPA12B Tg mice after stroke, L‐NAME significantly reduced capillary counts as indicated by immunostaining for CD31 at 28 days post‐stroke." (PMID 29411514, 2018). "Immunoblotting analysis demonstrated that HSPA12B expression was increased significantly by 5.7‐fold 24 hrs post‐stroke compared to sham controls (P < 0.01)." (PMID 29411514, 2018). "The data suggest that HSPA12B promoted functional recovery and survival after stroke in an eNOS‐dependent mechanism." (PMID 29411514, 2018). "We observed that HSPA12B Tg mice have promoted functional recovery and increased survival post‐stroke, concomitant with increased angiogenesis and neurogenesis." (PMID 29411514, 2018). "In this study, we demonstrated that overexpression of HSPA12B increased both BrdU‐positive and BrdU/NeuN‐positive cells in hippocampus after stroke, suggesting HSPA12B promoted neurogenesis in stroke brains." (PMID 29411514, 2018). "Stroke increased capillary counts and areas in both HSPA12B Tg and WT mice, respectively, compared with their sham controls (P < 0.01)." (PMID 29411514, 2018). "We then evaluated the roles of up‐regulated HSPA12B in mice survival at chronic phase of stroke using HSPA12B Tg mice." (PMID 29411514, 2018). "Also, a significant delayed neurological recovery was observed in HSPA12B‐Tg mice that administrated with L‐NAME immediately after stroke (P < 0.01)." (PMID 29411514, 2018). "However, administration with eNOS inhibitor L‐NAME diminished the HSPA12B‐induced protection in neurological functional recovery and mice survival post‐stroke." (PMID 29411514, 2018). "In this study, we observed an increased angiogenesis in HSPA12B Tg mice after stroke, suggesting facilitating angiogenesis could contribute to the promotion of functional recovery by HSPA12B." (PMID 29411514, 2018). "In addition, a role of eNOS has been identified in regulating functional recovery in HSPA12B Tg mice post‐stroke." (PMID 29411514, 2018). "Importantly, 113.3% more BrdU+ cells were co‐stained with NeuN in HSPA12B Tg mice compared to WT mice, indicating a promoted neurogenesis in HSPA12B Tg mice after stroke." (PMID 29411514, 2018). "Targeting HSPA12B expression may have a therapeutic potential for the stroke‐evoked functional disability and mortality." (PMID 29411514, 2018). "The increase in HSPA12B expression persisted to 7 days post‐stroke (P < 0.01)." (PMID 29411514, 2018). "However, HSPA12B Tg mice exhibited significant higher scores than those in the time‐matched WT mice post‐stroke (P < 0.01 or 0.05), respectively." (PMID 29411514, 2018). "However, HSPA12B Tg mice demonstrated significant more arteriole counts and areas by 56.3% and 236.0%, respectively, compared with WT mice post‐stroke (P < 0.01 or 0.05)." (PMID 29411514, 2018).
Stroke (continued). "However, the stroke‐induced up‐regulation of α‐SMA was enhanced in HSPA12B Tg mice compared with WT mice (P < 0.01)." (PMID 29411514, 2018). "Interestingly, HSPA12B Tg mice showed enhanced peri‐infarct angiogenesis (examined 28 days post‐stroke) and hippocampal neurogenesis (examined 7 days post‐stroke), respectively, compared to WT mice." (PMID 29411514, 2018). "Interestingly, HSPA12B Tg mice showed significant higher levels of TGF‐β1 by 55.7% than those in WT mice post‐stroke (P < 0.01)." (PMID 29411514, 2018). "Notably, the stroke‐induced increase in p‐eNOS/eNOS ratio was enhanced by 77.7% in HSPA12B Tg mice compared with WT mice (P < 0.01)." (PMID 29411514, 2018). "The results suggest that HSPA12B promotes functional recovery after stroke." (PMID 29411514, 2018). "However, the stroke‐induced abnormalities of neuronal morphology in all fields of hippocampus were significantly attenuated in HSPA12B Tg mice, respectively, compared with that in WT mice." (PMID 29411514, 2018). "Indeed, we revealed that the promoted angiogenesis and neurogenesis were concomitant with the enhanced eNOS activation and TGF‐β1 expression in HSPA12B Tg mice post‐stroke." (PMID 29411514, 2018). "Notably, the stroke‐induced increases of capillary counts and areas were enhanced in HSPA12B Tg mice by 53.3% and 99.8%, respectively, compared with WT mice (P < 0.05)." (PMID 29411514, 2018). "Importantly, overexpression of HSPA12B improved recovery of spontaneous movement activity (including speed and distance), symmetry of movement, floor walking, bean walking and response to vibrissae touch after stroke." (PMID 29411514, 2018). "Pre‐administration with L‐NAME decreased neurological scores significantly in HSPA12B Tg mice within 21 days post‐stroke compared with the time‐matched HSPA12B Tg mice without L‐NAME administration (P < 0.01 or 0.05), respectively." (PMID 29411514, 2018). "The stroke‐induced eNOS phosphorylation and TGF‐β1 expression were augmented in HSPA12B Tg mice." (PMID 29411514, 2018). "Interestingly, administration with L‐NAME significantly decreased mice survival within 28 days post‐stroke in HSPA12B Tg mice compared with HSPA12B Tg mice that without L‐NAME administration (P < 0.05)." (PMID 29411514, 2018).
tumor (5 papers, 2015 to 2024). "HSPA12B secreted by tumor-associated endothelial cells induces M2 polarization of macrophages by activating the PI3K/Akt/mTOR signaling pathway, thus promoting the formation of the immunosuppressive microenvironment within tumors." (PMID 34712697, 2021). "The ucRNA, uc.454, can negatively regulate its direct target gene Hspa12b to induce apoptosis of tumor cells, therefore acting as a tumor suppressor." (PMID 37036543, 2023). "In this study, we provided first evidence for that HSPA12B, which expresses predominantly in endothelial cells, stimulated lung tumor growth as reflected by a significant increase in tumor number and tumor burden." (PMID 25909170, 2015). "Most importantly, tumor burden was comparable between celecoxib-treated WT and celecoxib-treated Tg mice, suggesting that Cox-2 inhibition completely suppressed HSPA12B-induced tumor growth." (PMID 25909170, 2015). "TECs can participate in the occurrence, development, and metastasis of tumors by secreting cytokines such as interleukin, VEGF-A, and Heat Shock 70 kDa Protein 12B HSPA12B, as well as exosomes to activate receptors on tumor cells, support tumor metabolism, or suppress anti-tumor immune responses." (PMID 37666813, 2023). "We counted the numbers of pathways affected by each HSP; the results suggested that HSPA1L, HSPA12B, HSPA6, HSPA7 and HSPA12A may influence the activity of most cancer-related pathways and thus potently affect tumor development." (PMID 34712697, 2021).
cancer (3 papers, 2020 to 2024). A tumor composed of atypical neoplastic, often pleomorphic cells that invade other tissues. "For example, HSPA12B was positively enriched in 23 cancer types, including LUAD (FDR < 0.0001)." (PMID 33225964, 2020). "These HSP70-specific inhibitors may not distinguish HSPA9 from HSPA12B, which may lead to complicated consequences in anti-cancer therapy." (PMID 33225964, 2020).
infection (2 papers, 2015 to 2023). The state of being infected such as from the introduction of a foreign agent such as serum, vaccine, antigenic substance or organism. "Overexpression of HSPA12B in HUVECs was achieved by infection with recombinant adenoviruses encoding green fluorescence protein-HSPA12B." (PMID 25545050, 2015).
HSPA12B also shares sentences with these, for which no sentence is quoted: cardiovascular disease (3 papers); endotoxemia (3); colon cancer (2); atherosclerosis (1); colorectal cancer (1); endometrial cancer (1); head and neck squamous cell carcinoma (1); lung adenocarcinoma (1); Lung Disease (1); lung squamous cell carcinoma (1); myocardial ischemia (1); neuroblastoma (1); renal carcinoma (1); uterine corpus endometrial carcinoma (1).